TCP10L (t-complex 10 like)
Description:
May be involved in transcriptional regulation. Has in vitro transcription inhibition activity. Acts as a tumor suppressor in hepatocellular carcinoma (HCC) cells.
Synonyms: TCP10A-1; PRED77; C21orf77; LINC00846; TCP10A-2
Tractability: No criterion of Open Targets' tractability assessment is met for any kind of drug.
Gene: Protein-coding gene on chromosome 21 (32,497,967 to 32,587,373, reverse strand). Ensembl gene ENSG00000242220.
Subcellular location: Nucleus
Gene Ontology:
Molecular function: DNA-binding transcription factor binding; identical protein binding; protein binding; transcription corepressor activity
Biological process: negative regulation of transcription by RNA polymerase II
Cellular component: nucleus
Genetic constraint (gnomAD): Loss-of-function variants: 11 observed, 20.49 expected, observed/expected ratio (o/e) 0.54, 90% interval 0.34 to 0.89. The upper end of that interval is the gene's LOEUF score, 0.89, which puts it in group 3 of 6, group 1 being the genes least tolerant of losing a copy. Missense variants: 247 observed, 277 expected, observed/expected ratio (o/e) 0.89, 90% interval 0.8 to 0.99. Synonymous variants: 96 observed, 102.78 expected, observed/expected ratio (o/e) 0.93, 90% interval 0.79 to 1.11.
Homologues: Orthologues: chimpanzee TCP10L (72% identical), rat Tcp10b (25% identical), mouse Tcp10c (24% identical), mouse Tcp10a (23% identical), mouse Tcp10b (23% identical), tropical clawed frog tcp10l2 (21% identical), Drosophila melanogaster Sas-4 (17% identical). Paralogues in human: CPAP (22% identical).
Diseases named in the same sentence as TCP10L in open-access papers:
TCP10L is named in the same sentence as 2 diseases in open-access papers, as found by Europe PMC text mining. Sharing a sentence is not in itself a finding about the gene and the disease. The quoted sentences say what the papers report.
Infertility (1 paper, 2019). "These genes play important roles in cell proliferation (RFX4, FOXM1, ASF1B), differentiation during spermatogenesis (CATSPERG, SPDYA, SPATA16, TSACC, TCP10L, DPY19L2) and motility of sperm cells during fertilization (DNAAF1); mutations in these genes may lead to infertility." (PMID 31671693, 2019).
TCP10L also shares sentences with these, for which no sentence is quoted: tumor (1 paper).